LIG3 (DNA ligase 3)
Description:
Isoform 3 functions as a heterodimer with DNA-repair protein XRCC1 in the nucleus and can correct defective DNA strand-break repair and sister chromatid exchange following treatment with ionizing radiation and alkylating agents. Isoform 1 is targeted to mitochondria, where it functions as a DNA ligase in mitochondrial base-excision DNA repair.
Synonyms: LIG3alpha; LIG2; MTDPS20
Tractability: Small molecule: a structure with a bound ligand is known; it has a high-quality binding pocket. PROTAC: ubiquitination databases record sites on it; its protein half-life has been measured; a small molecule that binds it is known.
Target class: Enzyme; Ligase
Safety:
Unwanted effects reported when the protein is acted on. In parentheses: how it was acted on, where the effect was seen, and who reports it.
grade 3-4 neutropenia (source: ClinPGx)
Gene: Protein-coding gene on chromosome 17 (34,980,462 to 35,009,743, forward strand). Ensembl gene ENSG00000005156.
Subcellular location: Mitochondrion (Isoform 1); Mitochondrion (Isoform 2); Nucleus (Isoform 3); Nucleus (Isoform 4)
Subcellular location (Human Protein Atlas): Nucleoplasm
Pathways (Reactome):
DNA Repair: APEX1-Independent Resolution of AP Sites via the Single Nucleotide Replacement Pathway; Gap-filling DNA repair synthesis and ligation in GG-NER; Gap-filling DNA repair synthesis and ligation in TC-NER; HDR through MMEJ (alt-NHEJ); Resolution of AP sites via the single-nucleotide replacement pathway
DNA Replication: Strand-asynchronous mitochondrial DNA replication
Gene Ontology:
Molecular function: DNA ligase (ATP) activity; DNA ligase activity; protein binding; ATP binding; DNA binding; zinc ion binding
Biological process: base-excision repair; double-strand break repair; mitochondrial DNA repair; negative regulation of mitochondrial DNA replication; V(D)J recombination; base-excision repair, gap-filling; double-strand break repair via homologous recombination; lagging strand elongation; regulation of DNA repair; DNA biosynthetic process; DNA recombination; DNA repair; double-strand break repair via alternative nonhomologous end joining; mitochondrion organization; negative regulation of DNA metabolic process
Cellular component: mitochondrion; nucleoplasm; nucleus; DNA ligase III-XRCC1 complex; mitochondrial matrix; site of DNA damage; nuclear lumen
Genetic constraint (gnomAD): Loss-of-function variants: 58 observed, 115.17 expected, observed/expected ratio (o/e) 0.5, 90% interval 0.41 to 0.63. The upper end of that interval is the gene's LOEUF score, 0.63, which puts it in group 2 of 6, group 1 being the genes least tolerant of losing a copy. Missense variants: 1,093 observed, 1,334.7 expected, observed/expected ratio (o/e) 0.82, 90% interval 0.78 to 0.86. Synonymous variants: 422 observed, 498.22 expected, observed/expected ratio (o/e) 0.85, 90% interval 0.78 to 0.92.
Gene-disease validity (ClinGen):
ClinGen rates the evidence that LIG3 causes each of these diseases.
mitochondrial disease (autosomal recessive): Definitive.
Homologues: Orthologues: chimpanzee LIG3 (99% identical), macaque LIG3 (94% identical), rabbit LIG3 (91% identical), guinea pig LIG3 (91% identical), pig LIG3 (91% identical), dog LIG3 (89% identical), mouse Lig3 (88% identical), rat Lig3 (86% identical), tropical clawed frog lig3 (67% identical), zebrafish lig3 (65% identical), Drosophila melanogaster DNAlig3 (33% identical), Caenorhabditis elegans K07C5.3 (12% identical), and 1 more. Paralogues in human: LIG1 (20% identical), LIG4 (16% identical).
Diseases named in the same sentence as LIG3 in open-access papers:
LIG3 is named in the same sentence as 53 diseases in open-access papers, as found by Europe PMC text mining. Sharing a sentence is not in itself a finding about the gene and the disease. The quoted sentences say what the papers report.
breast cancer (9 papers, 2015 to 2025). A primary or metastatic malignant neoplasm involving the breast. "Kaplan-Meier analysis associated high LIG3 expression with improved survival in breast cancer and AML, suggesting its role as a prognostic biomarker." (PMID 40493574, 2025). "We further explored the association between the LIG3 gene and the survival rate for patients with breast cancer, bladder cancer, AML, and hepatocellular carcinoma." (PMID 40493574, 2025). "Notably, one recent preclinical study in mice showed that depleting LIG3 renders BRCA1-deficient mammary tumors sensitive to poly (ADP-ribose) polymerase (PARP) inhibitors." (PMID 40768895, 2025). "Moreover, genetic polymorphisms of LIG3 are strongly related to breast cancer prognosis." (PMID 31737108, 2019). "The Kaplan-Meier analysis demonstrated a significant correlation between high LIG3 expression and improved survival in breast cancer (HR: 0.81, p = 0.00093), and AML (HR: 0.67, p = 3e-05), respectively." (PMID 40493574, 2025). "Surprisingly, breast cancer patients with LIG3 rs1052536 tend to demonstrate longer progression-free survival." (PMID 31737108, 2019). "For instance, should breast cancer recur in the patient from which PDX-BCX1 and tamoxifen-resistant sublines were derived; our progress in NSG-Pro mice predicts that PARP plus LIG3 inhibitors would be effective." (PMID 34524841, 2021). "The Kaplan-Meier analysis demonstrated that high LIG3 expression correlates with improved survival in breast cancer and AML but not in bladder or liver cancers." (PMID 40493574, 2025).
neuroblastoma (7 papers, 2017 to 2025). Neuroblastoma (NB) is the most common solid, extracranial childhood tumor. "This is the first study to assess the associations between LIG3 SNPs (rs1052536 and rs4796030) and susceptibility to neuroblastoma in Chinese children; however, there are several limitations." (PMID 31737108, 2019). "We investigated the correlation between neuroblastoma susceptibility and two LIG3 polymorphisms (rs1052536 C>T and rs4796030 A>C) among 469 neuroblastoma patients and 998 healthy controls from China." (PMID 31737108, 2019). "The expression of FEN1, PARP1, and DNA ligase 3 significantly increases in high-risk neuroblastoma." (PMID 41189817, 2025). "Therefore, we conducted a three-center case-control study including 469 neuroblastoma patients and 998 controls to investigate the association between LIG3 gene polymorphisms and neuroblastoma susceptibility in Chinese children." (PMID 31737108, 2019). "If this hypothesis can be further validated, the use of mutant genes to induce LIG3 loss-of-function may be useful for the treatment of high-risk neuroblastoma patients." (PMID 31737108, 2019). "Nevertheless, whether LIG3 polymorphisms contribute to neuroblastoma risk remains unknown." (PMID 31737108, 2019). "LIG3 polymorphisms influencing expression may contribute to neuroblastoma susceptibility." (PMID 31737108, 2019). "The high expression of DNA ligase 3, PARP1, and FEN1 is significantly associated with poor overall survival in neuroblastoma." (PMID 41189817, 2025). "However, whether LIG3 polymorphisms are also associated with neuroblastoma risk remains unclear." (PMID 31737108, 2019). "In addition, they also found that patients with high expression of LIG3 in neuroblastoma cells had poorer prognoses." (PMID 31737108, 2019). "In conclusion, these results do not support a significant association between LIG3 gene polymorphisms and susceptibility to neuroblastoma; it is necessary to expand the sample size and conduct epidemiological studies on additional polymorphic loci in different ethnic groups." (PMID 31737108, 2019). "The inhibition of DNA ligase 3 or PARP1 enhances the accumulation of DSBs and promotes apoptotic cell death in neuroblastoma cells." (PMID 41189817, 2025). "Previous studies discovered that LIG1, LIG3, and PARP1 protein were upregulated in tumorigenic neuroblastoma cells." (PMID 33194676, 2020). "Reduction in LIG3 and LIG1 expression levels in neuroblastoma cells led to DSB accumulation and cell death." (PMID 31737108, 2019). "Thus, LIG3 may have a tumor-promoting role in neuroblastoma." (PMID 31737108, 2019). "MMEJ machineries including DNA ligase III (LIG3), DNA ligase I (LIG1), and poly(ADP-ribose polymerase 1) (PARP1) are highly expressed in neural crest stem cells, the cell of origin for neuroblastoma, and thought to contribute to the tumor's ability to survive double-stranded break triggering events." (PMID 37457440, 2023). "Inhibition of LIG1 and LIG3 led to DSB accumulation and cell death in neuroblastoma, suggesting the alt-NHEJ pathway as a critical function in cancer cell survival and progression HDACI differentially acetylated DNA repair factors to inhibit NHEJ activity in cancer cells." (PMID 33194676, 2020). "Fourth, whether LIG3 SNPs are closely related to prognosis of neuroblastoma was not studied in this study, which needs to be studied further." (PMID 31737108, 2019). "Since LIG3 SNPs can affect the expression and activity of LIG3, we speculate that neuroblastoma patients with LIG3 SNPs may have longer overall survival and (or) tumor-free survival than those with higher expression of LIG3 mRNA or without these SNPs, although this speculation needs confirmation." (PMID 31737108, 2019).
multiple myeloma (5 papers, 2019 to 2023). "For example, a recent study revealed that targeting the MALAT1/PARP1 (poly ADP-ribose polymerase 1) / LIG3 (DNA Ligase 3) complex resulted in DNA damage and apoptosis in multiple myeloma." (PMID 36829256, 2023). "Taken together, our findings demonstrate that myeloma cells are addicted to LIG3, which can be effectively inhibited by miR-22, promoting a novel axis of genome stability regulation." (PMID 30120376, 2019). "Furthermore, MALAT1 has been shown to modulate the alternative NHEJ (A-NHEJ) pathway by directly interacting with LIG3 and PARP1 in multiple myeloma cells and targeting MALAT1 enhances sensitivity to PARPi or proteasomal inhibitors." (PMID 37812088, 2023). "DNA Ligase III (LIG3) exerts a pivotal role in Alternative-Non-Homologous End Joining Repair (Alt-NHEJ), an error-prone DNA repair pathway often up-regulated in genomically unstable cancer, such as Multiple Myeloma (MM)." (PMID 36273153, 2022).
ovarian carcinoma (5 papers, 2021 to 2025). A malignant neoplasm originating from the surface ovarian epithelium. "Moreover, LIG3 rs4796030 AA/AC variant genotypes performed an increased risk of ovarian cancer under recessive model (adjusted OR=1.54, 95% CI=1.01-2.35, P=0.046), especially in the subgroups of higher BMI, early clinic stage and the carcinoma at the left." (PMID 33391423, 2021). "The genotyping results indicated that the PARP1 rs8679 and hOGG1 rs293795 A>G polymorphisms were associated with the decreased ovarian cancer risk under a dominant model, while LIG3 rs4796030 A>C polymorphism with an increased ovarian cancer risk under a recessive model." (PMID 33391423, 2021). "In research on ovarian cancer, overexpression of LIG1 and LIG3 is associated with aggressive phenotypes, platinum resistance and lower progression-free survival (PFS)." (PMID 39234248, 2024). "We have previously shown that XRCC1, a key scaffolding protein and a partner for LIG3 or LIG1 is a key predictor of platinum sensitivity in ovarian cancer." (PMID 34373746, 2021). "In the current study, we analyze the associations between 19 SNPs of six BER-related genes (hOGG1, APE1, PARP1, FEN1, LIG3 and XRCC1) and ovarian cancer risk by genotyping method in 196 patients and 272 controls." (PMID 33391423, 2021). "However, mechanistic studies will be required to confirm the role of mitochondrial LIG3 in platinum resistance in ovarian cancers." (PMID 34373746, 2021). "Therefore, we first tested LIG3 levels in LIG1 depleted ovarian cancer cells." (PMID 34373746, 2021). "In co-immunoprecipitation experiments, in ovarian cancer cell lines, we also observed that Mre11 physically interacted with Nbs1, Rad50, XRCC1 and LIG3 consistently in PEO1 cells." (PMID 35853939, 2022). "Given the key roles played by LIG1, LIG3 and LIG4 in genomic integrity 8 and the response of cancer cells to therapy, we investigated their role in ovarian cancer pathology and potential as novel therapeutic targets." (PMID 34373746, 2021). "In this two-center case-control study, 19 potentially functional SNPs in six BER-related genes (hOGG1, APE1, PARP1, FEN1, LIG3 and XRCC1) was genotyped in 196 ovarian cancer cases and 272 cancer-free controls." (PMID 33391423, 2021). "LIG1, LIG3 and LIG4 expression profiling in epithelial ovarian cancers: We initially evaluated LIG1, LIG3 and LIG4 expression at protein and transcriptional level in clinical cohorts of epithelial ovarian cancers." (PMID 34373746, 2021). "This is the first comprehensive study of LIG1, LIG3 and LIG4 in epithelial ovarian cancers." (PMID 34373746, 2021). "Whether LIG1, LIG3 and LIG4 can influence ovarian cancer pathogenesis and therapeutics is largely unknown." (PMID 34373746, 2021).
acute myeloid leukemia (4 papers, 2018 to 2025). Acute myeloid leukemia (AML) is a group of neoplasms arising from precursor cells committed to the myeloid cell-line differentiation. "Non-synonymous SNPs (nsSNPs) in the LIG3 gene are linked to genomic instability and increased cancer risk, particularly acute myeloid leukemia (AML)." (PMID 40493574, 2025). "PARP1 and LIG3 are found up-regulated in acute myeloid leukemia (AML) patients as compared to healthy individuals, and most importantly, their expression was strictly associated with chromosomal translocations occurrence." (PMID 33808562, 2021). "Here, we examined the expression levels of the maincomponents of alt-NHEJ (PARP1 and LIG3) in acute myeloid leukemia (AML) patients and assessed their potential correlationwith the formation of chromosomal translocations." (PMID 29633598, 2018).
gallbladder cancer (3 papers, 2021 to 2024). "In gallbladder cancer, RACGAP1 is upregulated in targets like DNA ligase 3 (LIG3) to mediate cell growth promotion and apoptosis reduction." (PMID 39858398, 2024). "In gallbladder cancer, RACGAP1 sustains LIG3 protein expression through interacting with and stabilizing LIG3 to reduce apoptosis and facilitate cells growth." (PMID 38898473, 2024).
leukemia (3 papers, 2018 to 2020). A malignant (clonal) hematologic disorder, involving hematopoietic stem cells and characterized by the presence of primitive or atypical myeloid or lymphoid cells in the bone marrow and the blood. "It has been shown that DNA ligase 3 (LIG3) proteins activate leukemia via a transcriptional error." (PMID 33255998, 2020).
adenoma (2 papers, 2013 to 2022). A neoplasm arising from the epithelium. "We observed that the association between folate and adenoma risk was modified by two LIG3 tagSNPs (rs1052536 interaction pgene = 0.006, interaction ppathway = 0.081; rs3744358 interaction pgene = 0.032, interaction ppathway = 0.451)." (PMID 23951112, 2013). "Finally, we found evidence that the LIG3 rs1052536 SNP modified the association between alcohol intake and adenoma risk." (PMID 23951112, 2013). "In addition, LIG3 SNPs rs1052536 and rs3744358 modified the association between dietary folate intake and adenoma risk." (PMID 23951112, 2013).
colorectal adenoma (2 papers, 2013 to 2022). An adenoma that arises from the colon or rectum. "Moreover, we observed evidence that SNPs in other BER genes modified the effect of smoking (MUTYH, OGG1), alcohol (LIG3), and dietary folate (LIG3) on colorectal adenoma risk." (PMID 23951112, 2013).
colorectal cancer (2 papers, 2016 to 2018). A primary or metastatic malignant neoplasm that affects the colon or rectum. "In addition, polymorphisms of EXO1, LIG3, and PolB may modulate the risk of colorectal cancer by decreasing (PolB) or increasing (LIG3 and EXO1) the chance of malignant transformation." (PMID 26649135, 2016). "HCT116 cells (a human colorectal cancer cell line) undergoing a telomeric crisis require the activity of DNA ligase III (LIG3), but not DNA ligase IV (LIG4) to escape a telomere crisis." (PMID 30680069, 2018).
lung adenocarcinoma (2 papers, 2016 to 2019). A carcinoma that arises from the lung and is characterized by the presence of malignant glandular epithelial cells. "The interaction between EXOG with APE1, PolG or Lig3, but not between nuclear-specific DNA repair enzymes FEN1 and PolB, was markedly reduced by H2S biosynthesis inhibition in lung adenocarcinoma (but not in normal epithelial cells)." (PMID 27808278, 2016).
lung carcinoma (2 papers, 2019 to 2025). "Significant associations with lung cancer and polymorphisms in genes involved in DNA damage sensing (ATM) and, in four genes encoding proteins involved in mismatch repair (LIG1, LIG3,MLH1, and MSH6) found." (PMID 40958859, 2025).
chronic intestinal pseudo‐obstruction (1 paper, 2025). "Here, we discuss the evidence for DNA repair defects in enteric neuropathies, most notably, the reported relationship between inherited mutations in RAD21 and LIG3 with chronic intestinal pseudo‐obstruction and mitochondrial gastrointestinal encephalomyopathy disorders, respectively." (PMID 39004995, 2025).
chronic myelogenous leukemia (1 paper, 2013). "The Werner syndrome helicase (WRN), together with LIG3, was found upregulated in chronic myelogenous leukemia (CML), where several D-NHEJ activities are suppressed." (PMID 23675572, 2013).
colon cancer (1 paper, 2016). "The present paper examines the impact of polymorphisms of PolB, LIG3, and EXO1 of the BER repair system on the modulation of the risk of colon cancer." (PMID 26649135, 2016).
esophageal cancer (1 paper, 2017). A primary or metastatic malignant neoplasm involving the esophagus. "Polymorphisms in the LIG3 gene have been associated with increased risk of several cancers such as colon, lung, and esophageal cancer." (PMID 28415781, 2017).
gallstones (1 paper, 2021). Solid crystalline precipitates in the biliary tract, usually formed in the gallbladder, resulting in the condition of cholelithiasis. "Our data showed that RACGAP1 expression correlates to the presence of gallstones in GBC patients, and RACGAP1 is involved in the LIG3-dependent DNA repair pathway." (PMID 34239347, 2021).
Insulin resistance (1 paper, 2023). Increased resistance towards insulin, that is, diminished effectiveness of insulin in reducing blood glucose levels. "Furthermore, the occurrence of insulin resistance in patients with steatosis depended on various LIG3 genetic variants." (PMID 37511066, 2023).
intestinal motility disorders (1 paper, 2025). "Therefore, mutations in the LIG3 gene may lead to mitochondrial diseases characterized by major intestinal motility disorders, brain diseases, and neuromuscular abnormalities." (PMID 40646787, 2025).
invasive carcinoma (1 paper, 2021). A carcinoma that is not confined to the epithelium, and has spread to the surrounding stroma. "Using cBioPortal, a breast-invasive carcinoma dataset was used to analyze LIG1 and LIG3 alterations, including mutations, putative copy-number alterations from GISTIC and mRNA expression z-scores relative to diploid samples (RNA Seq V2 RSEM)." (PMID 34825062, 2021).
plasma cell leukemia (1 paper, 2019). An aggressive plasma cell neoplasm characterized by the presence of neoplastic plasma cells in the peripheral blood. "Notably, LIG3 mRNA expression progressively increased in plasma cells from healthy donors (N) to MM and to plasma cell leukemia (PCL) patients and was the most expressed among DNA ligases." (PMID 30120376, 2019).